Y_RNA (Y RNA )
Gene: Miscellaneous RNA gene on chromosome 15 (39,922,782 to 39,922,886, reverse strand). Ensembl gene ENSG00000200305.
Homologues: Orthologues: chimpanzee Y_RNA (99% identical), macaque Y_RNA (84% identical). Paralogues in human: Y_RNA (89% identical), RNY3P1 (88% identical), Y_RNA (88% identical), RNY3 (87% identical), Y_RNA (87% identical), Y_RNA (86% identical), Y_RNA (85% identical), Y_RNA (84% identical), RNY3P14 (83% identical), Y_RNA (83% identical), Y_RNA (82% identical), RNY3P11 (81% identical), and 96 more.